SLC18A2 (solute carrier family 18 member A2)
Description:
Electrogenic antiporter that exchanges one cationic monoamine with two intravesicular protons across the membrane of secretory and synaptic vesicles. Uses the electrochemical proton gradient established by the V-type proton-pump ATPase to accumulate high concentrations of monoamines inside the vesicles prior to their release via exocytosis. Transports a variety of catecholamines such as dopamine, adrenaline and noradrenaline, histamine, and indolamines such as serotonin. Regulates the transvesicular monoaminergic gradient that determines the quantal size. Mediates somatodendritic dopamine release in hippocampal neurons, likely as part of a regulated secretory pathway that integrates retrograde synaptic signals (By similarity). Acts as a primary transporter for striatal dopamine loading ensuring impulse-dependent release of dopamine at the synaptic cleft (By similarity). Responsible for histamine and serotonin storage and subsequent corelease from mast cell granules.
Synonyms: VAT2; SVMT; VMAT2; SVAT; PKDYS2
Tractability: Small molecule: an approved drug acts on it; a structure with a bound ligand is known; a high-quality ligand is known; it belongs to a druggable protein family. Antibody: its Gene Ontology location is reachable by antibodies, with high confidence; UniProt predicts a signal peptide or a membrane-spanning region. PROTAC: a small molecule that binds it is known.
Target class: Electrochemical transporter; SLC18 family of vesicular amine transporters; Transporter; SLC superfamily of solute carriers
Safety:
Unwanted effects reported when the protein is acted on. In parentheses: how it was acted on, where the effect was seen, and who reports it.
extrapyramidal symptoms (source: ClinPGx)
Gene: Protein-coding gene on chromosome 10 (117,240,830 to 117,279,430, forward strand). Ensembl gene ENSG00000165646.
Subcellular location: Cytoplasmic vesicle, secretory vesicle, synaptic vesicle membrane; Cytoplasmic vesicle, secretory vesicle membrane; Cell projection, axon; Cell projection, dendrite
Subcellular location (Human Protein Atlas): Centrosome; Vesicles
Pathways (Reactome):
Neuronal System: Dopamine Neurotransmitter Release Cycle; Norepinephrine Neurotransmitter Release Cycle; Serotonin Neurotransmitter Release Cycle
Gene Ontology:
Molecular function: monoamine:proton antiporter activity; protein binding; monoamine transmembrane transporter activity; serotonin:sodium:chloride symporter activity; transmembrane transporter activity
Biological process: histamine uptake; serotonin uptake; aminergic neurotransmitter loading into synaptic vesicle; chemical synaptic transmission; negative regulation of reactive oxygen species biosynthetic process; neurotransmitter loading into synaptic vesicle; neurotransmitter transport; somato-dendritic dopamine secretion; establishment of localization in cell; histamine secretion by mast cell; organic hydroxy compound transport; proton transmembrane transport; serotonin secretion by mast cell; transmembrane transport
Cellular component: axon; clathrin-sculpted monoamine transport vesicle membrane; dendrite; membrane; plasma membrane; secretory granule membrane; synaptic vesicle; synaptic vesicle membrane; terminal bouton; dopaminergic synapse; transport vesicle membrane
Genetic constraint (gnomAD): Loss-of-function variants: 25 observed, 51.32 expected, observed/expected ratio (o/e) 0.49, 90% interval 0.35 to 0.68. The upper end of that interval is the gene's LOEUF score, 0.68, which puts it in group 2 of 6, group 1 being the genes least tolerant of losing a copy. Missense variants: 519 observed, 630.66 expected, observed/expected ratio (o/e) 0.82, 90% interval 0.76 to 0.88. Synonymous variants: 219 observed, 241.41 expected, observed/expected ratio (o/e) 0.91, 90% interval 0.81 to 1.01.
Gene-disease validity (ClinGen):
ClinGen rates the evidence that SLC18A2 causes each of these diseases.
brain dopamine-serotonin vesicular transport disease (autosomal recessive): Definitive. An infantile-onset neurometabolic disease characterized by dystonia, parkinsonism, nonambulation, autonomic dysfunction, developmental delay and mood disturbances.
Homologues: Orthologues: chimpanzee SLC18A2 (99% identical), macaque SLC18A2 (99% identical), pig SLC18A2 (94% identical), guinea pig SLC18A2 (93% identical), dog SLC18A2 (93% identical), mouse Slc18a2 (92% identical), rat Slc18a2 (92% identical), rabbit SLC18A2 (90% identical), tropical clawed frog SLC18A2 (79% identical), zebrafish slc18a2 (75% identical), Caenorhabditis elegans ZK550.2 (16% identical), Caenorhabditis elegans W05E10.1 (15% identical). Paralogues in human: SLC18A1 (64% identical), SLC18A3 (36% identical), SLC18B1 (20% identical).
Diseases named in the same sentence as SLC18A2 in open-access papers:
SLC18A2 is named in the same sentence as 90 diseases in open-access papers, as found by Europe PMC text mining. Sharing a sentence is not in itself a finding about the gene and the disease. The quoted sentences say what the papers report.
Parkinson disease (59 papers, 2006 to 2025). A progressive degenerative disorder of the central nervous system characterized by loss of dopamine producing neurons in the substantia nigra and the presence of Lewy bodies in the substantia nigra and locus coeruleus. "Until recently, analysis of the gene (SLC18A2) for VMAT2 within Parkinson’s disease cohorts was unable to conclude that variants in SLC18A2 result in increased likelihood of Parkinson’s disease." (PMID 33298952, 2020). "However, two of these genes (APLP2 and SLC18A2) are associated with low level biological process categories clearly related to Parkinson' disease: "G-protein coupled receptor protein signaling pathway" and "monoamine transport", respectively." (PMID 16762065, 2006). "For example, Slc18a2 (also known as VMAT2) was reported to enhance dopamine release and protect against Parkinson’s disease-related neurotoxin insult in vivo, while its deficiency contributes to dopamine neuron death in the brain." (PMID 36810115, 2023). "In the 10th injection, down-regulated genes were significantly enriched in terms of “Parkinson’s disease” and “Dopaminergic synapse” (such as Th, Drd2, Slc6a3, and Slc18a2)." (PMID 32997292, 2021). "Noteworthy, TH, dopamine receptor 2 (DRD2), SLC6A3/DAT, SLC18A2, tubulin beta 2A (TUBB2A), tubulin alpha 4A (TUBA4A), and tubulin beta 3 (TUBB3) were the 7 key genes enriched in the Parkinson disease pathway." (PMID 40259945, 2025). "The Parkinson’s disease and Alzheimer’s disease pathways in the SncaG51D/G51D cortex were significant due to down-regulation of proteins involved in oxidative phosphorylation (NDUFAB1, COX5A, NDUFB8), and in the case of PD dopamine transport (SLC18A2)." (PMID 40574971, 2025).
depression (35 papers, 2014 to 2025). "A specific haplotype in SLC18A2, the gene encoding VMAT-2, was significantly associated with depression symptoms in men." (PMID 30618598, 2018). "In the present study, Cordyceps polypeptide treatment could promote the expression of Slc18a2 and thereby promoted the secretion of neurotransmitters in mice to reduce dyskinesia and depression-like behavior, which may be conducive to the improvement of learning and memory." (PMID 29736181, 2018).
Huntington disease (18 papers, 2017 to 2025). Huntington disease (HD) is a rare neurodegenerative disorder of the central nervous system characterized by unwanted choreatic movements, behavioral and psychiatric disturbances and dementia. "inhibitor (Deutetrabenazine) is proved to be effective in the cure of involuntary movements in patients with tardive dyskinesia, and the SLC18A2 blocker (Tetrabenazine) is the only US Food and Drug Administration-approved drug for Huntington’s disease." (PMID 34899276, 2021).
schizophrenia (17 papers, 2011 to 2025). A major psychotic disorder characterized by abnormalities in the perception or expression of reality. "Polymorphisms in the VMAT2 (SLC18A2) gene may be associated with schizophrenia, bipolar disorder, and other neurological/psychiatric disorders." (PMID 39685567, 2024).
bipolar disorder (9 papers, 2011 to 2026). A disorder of the brain that causes unusual shifts in mood, energy, activity levels and the ability to carry out day-to-day tasks. "While HTR1A, HTR2A, and HTR7 are known targets of lurasidone, MAOB, HTR3A, SLC18A2, and HTR1B were identified for the first time as targets of lurasidone potentially involved in its associated induction of acute manic episodes in people with bipolar depression." (PMID 40202273, 2025). "Our bioinformatics and computational analyses demonstrated that lurasidone may regulate the serotonergic synapse signaling pathway by targeting proteins such as MAOB, HTR1A, HTR2A, HTR3A, SLC18A2, HTR1B, and HTR7 to induce treatment‐emergent mania in people with bipolar depression." (PMID 40202273, 2025). "This study revealed that lurasidone may regulate the serotonergic synapse signaling pathway by interacting with the identified core targets MAOB, HTR1A, HTR2A, HTR3A, SLC18A2, HTR1B, and HTR7 to induce treatment‐emergent mania in people with bipolar depression." (PMID 40202273, 2025).
Dystonia (8 papers, 2015 to 2025). An abnormally increased muscular tone that causes fixed abnormal postures. "Among the dystonic children, 9 were diagnosed with CP, 3 with pantothenate kinase-associated neurodegeneration (PKAN), 3 with KMT2B, 2 with SLC18A2-related dystonia, 2 with WARS2, and 2 with suspected neurotransmitter disorder." (PMID 40531829, 2025). "Expanding the genes in the targeted next generation dystonia panels including SLC18A2 (VMAT2 deficiency), AADC gene (AADC deficiency), QDPR (DHPR deficiency) and PTS (PTPS deficiency) would preempt the necessity of CSF neurotransmitter metabolite measurements." (PMID 25758715, 2015). "Interestingly, a decrease in vesicular function because of SLC18A2 mutation could lead to brain dopamine-serotonin vesicular transport disease, including infantile parkinsonism-dystonia-2." (PMID 37089789, 2023).
epilepsy (5 papers, 2013 to 2024). A brain disorder characterized by episodes of abnormally increased neuronal discharge resulting in transient episodes of sensory or motor neurological dysfunction, or psychic dysfunction. "SLC18A2 is expressed in monoaminergic neurons of the central nervous system, and abnormal expression of SLC18A2 has been proposed to contribute to vulnerability toward epilepsy-related psychiatric disorders and cognitive impairment in adults." (PMID 34899276, 2021).
prostate carcinoma (4 papers, 2017 to 2026). A carcinoma that arises from epithelial cells of the prostate gland. "The group found that SLC18A2 mRNA expression levels were significantly decreased in prostate cancer samples, with low expression levels significantly associated with PSA recurrence after radical prostatectomy (multivariate hazard ratio (HR) 0.13, p < 0.05) suggestive of independent prognostic value." (PMID 30200254, 2018). "A cohort of 412 prostate cancer tissues and 45 benign prostate tissues were used to assess SLC18A2 mRNA expression." (PMID 30200254, 2018). "The low expression of SLC18A2 reduces OS in prostate cancer." (PMID 36829221, 2023). "In this study, we show that prostate cancer-specific hypermethylation of the eight genes AOX1, CCDC181 (C1orf114), GABRE, GAS6, HAPLN3, KLF8, MOB3B, and SLC18A2 can be detected by qMSP with very high sensitivity and specificity in scarce prostate needle biopsy samples taken at the time of diagnosis." (PMID 28084441, 2017).
Hypertension (3 papers, 2022 to 2025). The presence of chronic increased pressure in the systemic arterial system. "Furthermore, we first investigated the expression patterns of the hypertension drug‐related genes in COVID‐19 patients by data set mining and modeling, suggesting the molecules being potentially involved in both hypertension and COVID‐19 pathology, such as JUN, LST1, and SLC18A2." (PMID 35656698, 2022).
cocaine addicts (2 papers, 2012 to 2022). "Similarly, genes that are suggestive of cocaine addiction (KEGG ID: mmu05030) were upregulated in the HFD group compared with the STD group, but the expression of genes that are involved in these pathways (Th/Slc18a2/Drd2) were downregulated (or tempered) in the HF1G group (p = 0.01)." (PMID 35204296, 2022).
preeclampsia (2 papers, 2021 to 2022). Preeclampsia is a hypertensive disorder of pregnancy that is characterized by new-onset hypertension with proteinuria presenting after 20 weeks of gestation, and depending on mild or severe forms may initially present with severe headache, visual disturbances, and hyperreflexia. "Independent studies between the two samples showed that there were three genes with reduced expression and statistical differences in preeclampsia: SLC18A2, HDC, and MS4A2." (PMID 35782866, 2022).
synucleinopathies (2 papers, 2019 to 2024). "Our RNAseq analysis identified decreased transcription of the monoamine transporters Slc18a2 (VMAT2) and Slc6a3 (DAT), in early synucleinopathy." (PMID 38172128, 2024).
behavioral disorders (1 paper, 2021). "Out of those genes from SCL family, 12 genes (12/14) and 4 genes (including SLC18A2) were statistically and causally associated, respectively, with human behavioral disorders." (PMID 33800722, 2021).
glioma (1 paper, 2023). A benign or malignant brain and spinal cord tumor that arises from glial cells (astrocytes, oligodendrocytes, ependymal cells). "Abnormal SLC18A2 expression may also affect GB cells, since neuronal activity promotes glioma formation through autocrine, non-synaptic, as well as synaptic paracrine mechanisms using functional synapses between glioma cells and neurons, inducing tumor proliferation and progression." (PMID 37298344, 2023).
heart failure (1 paper, 2025). Inability of the heart to pump blood at an adequate rate to meet tissue metabolic requirements. "MR analysis identified significant causal associations between the genes implicated in BW loss (ADD3, HSPA12A, SLC18A2, PDZD8, DUSP5, CASP7) as well as EF% and LV volumes (GPC6, UGGT2, SLAIN1, POU4F1, MBNL2) in BXD mice post-DOX and heart failure (HF) outcomes in humans." (PMID 40321772, 2025).
infarction (1 paper, 2020). A localised pathological necrosis of tissue resulting from obstruction of the blood supply usually by a thrombus, an embolus, or vascular torsion. "Slc18a2 was upregulated in the rat infarction model and its candidate regulator, miR-1255b-5p, was also found to be upregulated in this study." (PMID 32354168, 2020).
memory impairment (1 paper, 2018). "The real-time quantitative PCR analysis of the expression of Pik3r5, Il-1β, and Slc18a2 further indicated that these three genes were all the key factors in the effects of Cordyceps polypeptide on the nervous system in the mouse model of learning and memory impairment." (PMID 29736181, 2018).
pneumonia (1 paper, 2025). An acute, acute and chronic, or chronic inflammation focally or diffusely affecting the lung parenchyma, caused by an infection in one or both of the lungs (by bacteria, viruses, fungi, or mycoplasma.). "Children diagnosed with PKAN, suspected neurotransmitter disease, SLC18A2, or GNAO1 were particularly noteworthy, as all had recurrent pneumonia." (PMID 40531829, 2025).
psychiatric disorder (8 papers, 2015 to 2025). A disorder characterized by behavioral and/or psychological abnormalities, often accompanied by physical symptoms. "Also, while SLC18A2 does not have differential expression in other psychiatric disorders, it is one of several serotonergic genes that facilitates the transport of vesicles containing serotonin to the presynaptic neuron, a process that has been associated with suicidal behavior." (PMID 37794117, 2023).
tumor (8 papers, 2003 to 2023). "DPP7, CDR2L exhibited higher and UNC5C, RAB3B, SLC18A2, GPRASP1, PCDH9 exhibited lower expression in tumor tissues (P<0.05)." (PMID 37384293, 2023).
neurological diseases (5 papers, 2018 to 2025). "Brain dopamine-serotonin vesicular transport disease is a rare neurological disease caused by mutations in the vesicular monoamine transporter 2 (VMAT2; encoded by SLC18A2), an H+ ATPase antiporter required for transport of neurotransmitters into presynaptic vesicles." (PMID 30266839, 2018).
cancer (4 papers, 2017 to 2023). A tumor composed of atypical neoplastic, often pleomorphic cells that invade other tissues. "We also report that SLC18A2, PLXNC1, and MRPL33 gene expression is associated with TrkA or KIT expression levels in both AML and NB, and these genes have a prognostic value for both cancers." (PMID 31681584, 2019). "A total of 20 target mRNAs of three miRNAs were predicted, among which seven target mRNAs—ASAP3, BCL2L2, LMF1, PPM1L, PTPN21, SLC18A2, and NR3C2—had prognostic value; PRKACB, PDCD4, RPS6KA5, and BCL2L2 were enriched in the miRNA cancer pathway." (PMID 36829221, 2023). "Consistent with results obtained from the TCGA-COAD cohort, six CRGs, including DPP7, GPRASP1, UNC5C, RAB3B, PCDH9, SLC18A2, were significantly downregulated, whereas CDR2L was upregulated in cancer tissues in comparison with paracancerous normal tissues." (PMID 37384293, 2023).
SLC18A2 also shares sentences with these, for which no sentence is quoted: Chorea (25 papers); Parkinsonism (21); Anxiety (14); diabetes (7); movement disorder (7); Obesity (7); Tics (6); alcoholism (5); Cognitive impairment (4); Dyskinesia (4); mood disorder (4); psychosis (4); Alzheimer disease (3); dementia (3); infection (3); insulinoma (3); neuroblastoma (3); neurodegenerative disease (3); somnolence (3); Apathy (2); developmental delay (2); Tourette’s disorder (2); type 1 diabetes mellitus (2); type 2 diabetes mellitus (2); AADC deficiency (1); alcohol abuse (1); Arrhythmia (1); attention deficit-hyperactivity disorder (1); autism (1); brain disease (1).
A further 38 diseases each share a sentence with SLC18A2 in 1 paper.